ENSG00000286264 (novel protein)
Synonyms: LOC114841035
Gene: Protein-coding gene on chromosome 11 (64,241,095 to 64,244,132, forward strand). Ensembl gene ENSG00000286264.
Homologues: Orthologues: mouse Gm51400 (74% identical).